ZEB1 (zinc finger E-box binding homeobox 1)
Diseases named in the same sentence as ZEB1 in open-access papers (continued):
Sharing a sentence is not in itself a finding about the gene and the disease.
tumor (continued). "SNAI1 was also shown to induce the expression of mesenchymal markers fibronectin and Zeb1, the latter of which is an EMT‐TF that can promote tumor invasiveness in vitro and is correlated with tumor cell differentiation in vivo." (PMID 28548345, 2017). "As IFN-γ activates ZEB1, which in turn suppresses LIF expression, ZEB1 expression can be queried as a surrogate measure for therapies that invoke tumor differentiation." (PMID 28246407, 2017). "We aimed to dissect how increased extracellular HA contributes to ZEB1-driven EMT and how its synthesis and secretion is regulated during tumor progression." (PMID 28086235, 2017). "In the early stages of MBC, EMT-TFs, like TWIST1, ZEB1/2, and SLUG, repress E-cadherin and β-catenin expression; promote EMT, cell motility and invasiveness; and permit the intravasation of tumor cells." (PMID 28423483, 2017). "Our in vivo model showed that CXB treatment significantly inhibited both overexpression of nuclear Slug and ZEB1 and nuclear FAK in the xenograft OSCC tumours." (PMID 28740192, 2017). "HULC was also recently shown to enhance epithelial-mesenchymal transition (EMT), which contributes to tumor metastasis and recurrence in HCC via a signaling pathway involving zinc finger E-box binding homeobox 1 (ZEB1) and miR-200a-3p." (PMID 30159431, 2017). "TGF‐β deposited in the surrounding stroma or secreted from tumor cells induces the expression of both ZEB1 and Snail1, thereby triggering EMT to promote tumor progression and metastasis." (PMID 28649800, 2017). "In summary, our study uncovered a key role for ZEB1 in the establishment of CSC properties and in promoting tumor initiation by breast CSCs." (PMID 28903350, 2017). "Mounting evidences indicated that tumor microenvironment harbored aberrant TGF-β expression activated the expression of transcription factor Slug/Snail2, ZEB1, and ZEB2, and contributed to the initiation of EMT." (PMID 29084594, 2017). "The ZEB1 (log 2fc=−2.28) and ZEB2 (log 2fc=−2.3) transcripts are also significantly overexpressed, implying induction of the EMT in the responder tumor." (PMID 28594404, 2017). "Several transcription factors, including Snail, Slug, Twist, ZEB1, and ZEB2, have been identified as inducers of EMT and tumor metastasis." (PMID 27549611, 2016). "In order to clarify the relationship between MAZ, ZEB1 and ZEB2 in HCC, we detected their expression in 75 pairs of HCC and adjacent non-tumor tissues." (PMID 27861158, 2016). "Moreover, differently from that found in the cell line, the generic silencing of FGFR2 was able to increase both ZEB1 and Snail1 expression already in untransfected cells, further supporting the hypothesis of the tumor suppressive role of the endogenously expressed FGFR2b." (PMID 26713601, 2016). "Although EMT is not completely dependent on EMT regulators such as Snail, Twist, and Zeb-1/-2, analysis of upstream signaling (i.e., TGF-β, EGF, Wnt) is necessary to understand tumor EMT more comprehensively." (PMID 26828526, 2016). "Levels of ZEB1 protein are reduced by the miR-200 microRNA family, and aberrant epigenetic silencing of miR-200 in human cancer cells and tumors promotes EMT, tumor cell adhesion, migration, invasion and metastasis." (PMID 26646320, 2016). "In the normal state, H19 compete with ZEB1 and PAX3, while the interaction between H19 and ZEB1 is ‘switch off’ in the tumor." (PMID 27580177, 2016). "N-cadherin levels have been shown to be elevated in cell lines expressing Snail and ZEB-1, as well as, in patients with higher FIGO tumor grade and metastasis." (PMID 27144941, 2016). "Target ZEB1/2 via the TGF‐β/ZEB/miR‐200 pathway, as well as change the tumour microenvironment to inhibit EMT and metastasis." (PMID 27027258, 2016). "We detected the expression of ZEB1 and ZEB2 in the 75 pairs of HCC and adjacent non-tumor tissues that MAZ expression had been measured by IHC." (PMID 27861158, 2016).
tumor (continued). "EMT, as well as tumor migration and invasion of HCC cells is promoted by the oncogene HOXD9; while ZEB1 knockdown inhibits these HOXD9-induced effects." (PMID 27412382, 2016). "Our finding of a direct molecular interaction of ZEB1 and YAP indicates novel strategies to interfere with tumour progression." (PMID 26876920, 2016). "A lower threshold of ZEB1 or TWIST1 is sufficient to induce stemness and tumor initiation, whereas further induction is necessary for EMT induction, invasion, and tumor metastasis." (PMID 27596438, 2016). "The ectopic expression of ZEB1 down‐regulates E‐cadherin and induces EMT in malignant tumour via binding with its conserved E‐boxes on promoter." (PMID 27027258, 2016). "The ZEB1 transcription factor, a known inducer of EMT and invasiveness, is now considered as a genuine oncogenic factor required for tumor initiation, cancer cell plasticity, and drug resistance in carcinomas." (PMID 27596438, 2016). "In this study, we used immunohistochemistry to study the expression of a panel of transcription factors (TWIST1, SNAI1/2, ZEB1 and ZEB2) and other genes intimately related to EMT (CDH1 and LAMC2) at the invasive tumor front of OSCC tissues." (PMID 26214683, 2015). "Strikingly, treatment with a mirVana miR-21 inhibitor, or silencing LPA1 or ZEB1 completely blocked LPA-induced cell migration in vitro, invasion and tumor cell bone colonization in vivo, which can be restored with a mirVana miR-21 mimic." (PMID 26098771, 2015). "mir-200 family plays critical roles in tumor development and progression through inhibiting EMT and suppressing tumor invasion by directly repressing the transcription factors ZEB1 and ZEB2." (PMID 25972084, 2015). "Then, we compared the mRNA levels of several TGF-β-related EMT-regulators including SNAI1, SNAI2, HMGA2, FOSL1, SP1, ZEB1, ZEB2 (SIP1), and TWIST1 in primary tumor tissues of MDA-MB-231-xenografted mice." (PMID 26462028, 2015). "Of these, ZEB1, which had the highest degree in the resulting ENA network, is a well-known EMT activator and tumor promoter that represses stemness-inhibiting microRNAs and mediates the loss of E-cadherin expression to allow cell detachment." (PMID 25390635, 2014). "Snail-1, Twist and Zeb1 are induced by TGF-β, a cytokine that is able to activate EMT and tumor invasion." (PMID 25428918, 2014). "It is evidenced that ZEB1 and ZEB2 expression is induced by a sudden changes in the tumor microenvironment such as varying oxygen tensions, exposing to ionizing radiation, contacting with chemotherapeutic agents, and or demethylating agents." (PMID 25197668, 2014). "To analyze the mechanisms of the overexpression of miR200c or knockdown of ZEB1 for reinforcing the antimelanoma efficacy of the tumor vaccine B16F10/GPI-IL-21, we detected the EMT-related molecular expression in tumor tissues from the immunized mice." (PMID 24625224, 2014). "We therefore measured the effects of embelin on the expression of E-cadherin, Snail, Slug, ZEB1, MMP-2 and MMP-9 in tumor tissues." (PMID 24694877, 2014). "One important HAT, p300, affects the regulation of Snail and ZEB1 in colon cancer, thereby contributing to EMT and tumor progression." (PMID 24840099, 2014). "LncRNA-ATB promotes and sustains EMT and tumor invasion via two mechanisms: on one hand, lncRNA-ATB up-regulates Zeb1 and Zeb2 by competitively binding the miR-200 family, which targets Zeb1 and Zeb2, thus acting as a ceRNA." (PMID 25428918, 2014). "During both normal development and tumor progression, EMT is orchestrated by a set of pleiotropically acting transcription factors (TFs), such as Twist, Snail, Slug, ZEB1/2 that together form an intricate transcriptional circuitry." (PMID 24840099, 2014). "We found that the top ranking TF, ZEB1, previously known for its role in epithelial to mesenchymal transition (EMT) and tumor metastasis, is a critical mediator of in vitro and in vivo adipogenesis, as it directly controls the majority of aGRN genes." (PMID 25163748, 2014).
tumor (continued). "ZEB1 and ZEB2, members of the ZEB family, have been shown to induce EMT through repression of E-cadherin and to promote tumor progression and metastatic spread." (PMID 24677166, 2014). "To address the functional significance of the miR200c overexpression or ZEB1 knockdown in B16F10 cells, we tested the EMT-related molecular expression in tumor tissues." (PMID 24625224, 2014). "Both ZEB1-shRNA and OVOL1 expression reduced the number of mice with tumor metastasis in multiple sites." (PMID 24124593, 2013). "Owing to above results we concluded that tumor cells obtained migratory and invasive ability indicated by MMP2 and MMP9 stimulation, whereas ZEB1 required further elucidation in other ccRCC cell lines." (PMID 24023875, 2013). "ZEB1/2 and SNAIs are known to alter E-cadherin mediated cellular adhesion whereas TWIST1 increases tumor seeding resulting in distant metastases." (PMID 23950888, 2013). "They target ZEB1 and ZEB2, transcriptional repressors of E-cadherin, and thereby inhibit EMT and tumor invasion." (PMID 23741524, 2013). "In contrast, our data suggests that increased tumour invasion is mediated by a change in N-cadherin dynamics, mediated through ROBO1 by ZEB1." (PMID 23818228, 2013). "The AKT inhibitor, GSK690693, inhibited AKT, blocked the expression of ZEB1 and vimentin and restored the expression of E-cadherin following IR, thus preventing the migration and EMT of the tumor cells." (PMID 24179501, 2013). "Studies have shown that by targeting the transcriptional repressors of E-cadherin, ZEB1 and ZEB2, the miR-200 family is involved in epithelial-to-mesenchymal transition (EMT) and tumor invasion." (PMID 24223734, 2013). "NP-siRNA-mediated knockdown of DCAMKL-1 resulted in upregulation of pri-miR-200a and downregulation of ZEB1 and ZEB2 with upregulation of E-cadherin in the HCT116 tumor xenografts." (PMID 21929751, 2011). "Zeb-1 is a crucial EMT activator and suppresses the expression of basement membrane components and cell polarity factors thereby promoting metastasis of tumor cells." (PMID 21909380, 2011). "The transcriptional repressor zinc-finger E-box binding homeobox 1 (ZEB1) is a crucial inducer of EMT in various human tumors, and it recently was shown to promote invasion and metastasis of tumor cells." (PMID 19912656, 2009). "Tumor cells exhibiting high SIGLEC15 expression demonstrated reduced epithelial–mesenchymal transition (EMT) tendencies compared to those with lower expression levels, potentially through the regulation of ZEB1 expression." (PMID 41158758, 2026). "Instead, Snail's tumor-promoting activity is largely mediated through its cooperation with EGR1/SP1 transcription factors on non-canonical TCACA promoter elements, which upregulate genes such as ZEB1, MMP9, and LEF1." (PMID 42152116, 2026). "Moreover, quantitative PCR on xenograft tumor samples revealed that CTGF, ZEB1, and vimentin expression exhibited the same pattern as tumor growth, but E-cadherin expression had the opposite effect." (PMID 41216500, 2026). "Similarly, miR-216a and miR-216b are significantly downregulated in patient serum and are known to inhibit oncogenic pathways across multiple tumor types by targeting KRAS, IGF2BP2, eIF4B, and ZEB1." (PMID 41596525, 2026). "However, DDR1 knockdown significantly reduced GSH levels and GPX4, SLC7A11 and ZEB1 expression and increased MDA and Fe2+ levels, as well as ACSL4, E‐cadherin, p‐YAP and p‐NF2 expression levels in tumour tissues." (PMID 40105492, 2025). "Interestingly, only PPARD expression positively correlated with an EMT-related gene signature formed by ZEB1, SNAI1, and SNAI2 in the tumor." (PMID 40607925, 2025).
tumor (continued). "In the hypoxic TME, ZEB1 promotes macrophage infiltration by activating the transcription of CCL8, which subsequently attracts macrophages via the CCR2-NF-κB pathway, enhancing TAM accumulation in the tumor microenvironment." (PMID 40304000, 2025). "Kröger and colleagues demonstrated that HMLER mammary cells with a hybrid/mixed E/M state co-expressed Snail and Zeb1, supporting the hypothesis that M13HS-2 and M13HS-8 tumor hybrids may also show a hybrid/mixed E/M phenotype." (PMID 40806166, 2025). "Interestingly, tumorous tissue contained more CD68+ cells and an increased share of ZEB1+ cells among those as compared to respective healthy tissue." (PMID 40595293, 2025). "This indicates a cell line-dependent contextual impact of ZEB1 in macrophages on tumor cell proliferation but not on tumoricidal CD8+ cell influx." (PMID 40595293, 2025). "Similarly, ZEB1/2 and Twist can also be regulated in an m6A-dependent manner, thereby affecting the EMT process of tumor cells." (PMID 40356596, 2025). "Preclinical in vitro studies showed that ZEB1 can promote the proliferation, colony formation, sphere formation and migration of HCC cells and markedly enhance tumor progression in vivo in diethylnitrosamine (DEN)-induced models and orthotopic xenografts of human cell lines." (PMID 41303618, 2025). "Notably, the transcription factors TWIST2 and ZEB1—key drivers of EMT and tumor invasiveness—were significantly downregulated in SET-type tumors." (PMID 41155518, 2025). "ZEB1 expression was significantly increased in PTC with LNM, whereas the majority of node-negative PTC cases exhibited negative staining, suggesting a possible function of ZEB1 in aggressive tumor behavior." (PMID 40787244, 2025). "Altogether, the study suggests that TGFβ/ZEB1 mediates the induction of EMT in iCCA, while targeting EMT failed to inhibit iCCA development or tumor metastasis, disputing the claims that EMT is a major molecular event leading to tumor metastasis." (PMID 41354626, 2025). "Zeb1 knockdown via short hairpin RNA (shRNA) in an AML mouse model induced by the MLL-AF9 oncogene led to reduced infiltration in the bone marrow during an in vivo study and impaired tumor cell invasion in an in vitro study." (PMID 39941895, 2025). "Loss of FAT1 function activates the Ca2+/calmodulin-dependent protein kinase II (CAMK2)–CD44–SRC axis, promoting YAP1 nuclear translocation and zinc finger E-box binding homeobox 1 (ZEB1) expression, thereby stimulating the mesenchymal state and increasing tumor stemness and metastasis." (PMID 41368628, 2025). "Importantly, the mentioned study demonstrated that the genetic downregulation of ZEB1 and Twist1 leads to a substantial decrease in invasion and growth in selected UVM cell lines, highlighting their indispensable roles in tumor progression." (PMID 40362553, 2025). "The protein levels of DEC1 and ZEB1 in GC tumor tissues were significantly higher than those in adjacent normal tissues." (PMID 40133270, 2025). "In addition, immunohistochemical analysis of tumor tissues showed that alpha-estradiol and (R)-(−)-ibuprofen inhibited the expression of GLI1, Zeb1 and Vimentin." (PMID 40255562, 2025). "Using immunostaining, we also found a significantly larger number of cells expressing the EMT markers ZEB1 and SNAIL/SLUG in PROM2+ tumours (respectively 68 ± 5 and 82 ± 6%) compared with PROM2‐ tumours (respectively 7 ± 6 and 11 ± 4%, p < .01 for the two markers)." (PMID 38515278, 2024). "Dedifferentiation in LUACs correlated with high PD-L1 expression (p < 0.001), with no/low β-catenin membranous staining (p = 0.024), with high ZEB1 expression in the tumor (p = 0.017), and with KC status (p = 0.034)." (PMID 38791897, 2024). "Analyzing the parental MM tumors, we could detect a variable fraction of MITF−/low/CDH1−/ZEB1+/CD271+ cells, proposing the existence of a MIC subpopulation in the primary tumor mass." (PMID 38191367, 2024).
tumor (continued). "To metastasize, tumor cells acquire invasive stem cell-like properties by hijacking the EMT program, gaining chemoresistance and stem-like traits regulated by EMT-inducing transcription factors such as Snail, Slug, Twist, and ZEB1/2." (PMID 39796130, 2024). "Finger Citron inhibits tumor cell proliferation and invasion and induces apoptosis by downregulating Cyc-D1, MMP and bcl-2 through siRNA-mediated Zeb1 silencing replication to promote Zeb1 overexpression." (PMID 38817861, 2024). "In summary, our findings demonstrate that the ZEB1/NuRD complex collaboratively suppressed the transcription of the tumor suppressor gene CLDN7, promoted glycolysis, and exerted an impact on tumor development, potentially signifying the discovery of novel CRC biomarkers." (PMID 39193340, 2024). "What is more, in mouse models of OC, TAMs required specific protein zinc finger E-box-binding homeobox 1 (ZEB1), for their tumor-promoting activity and TAMs with full ZEB1 gene expression turned out to enhance tumor growth as ZEB1 induces polarization of TAMs in the pro-tumor direction." (PMID 38892394, 2024). "Transcription factors like ZEB1, TWIST1 and NAI1, all of which could be potentially used for tumor therapy, regulate EMT-mediated tumor metastasis and drug resistance." (PMID 39877159, 2024). "The animals were sacrificed, and the tumor tissue from stressed animals exhibited increased mRNA expression of the EMT-related genes Twist1, Twist2, Zeb1, Zeb2, Slug, and PLAGL2 and increased protein expression of PLAGL2, Ki67 (a proliferation marker), N-cadherin, and Vimentin." (PMID 38689092, 2024). "In this study, the impact of using the established five tumour-based EMT markers consisting of E-cadherin (E-cad), β-catenin (β-cat), Snail, Zeb-1, and Fascin in combination with the stromal periostin (PN) on the prediction of CRC patients’ prognosis were invesigated." (PMID 38935747, 2024). "Additionally, H19 can promote tumor cell growth, invasion, and migration through the H19/miR-200a/CDK6/ZEB1 axis." (PMID 38715092, 2024). "Given the known role of ZEB1 in tumor cells to induce EMT, stemness, and chemoresistance, combined targeting of ZEB1 in fibroblast and tumor cells might act synergistically to improve CRC therapy." (PMID 38937629, 2024). "Another study found that glabridin inhibited EMT in breast cancer cells by upregulating E-cadherin and occludin, while downregulating vimentin, E-box-binding zinc finger protein 1 (Zeb1), and other critical EMT markers, thereby exerting a controlling effect on tumor invasion and metastasis." (PMID 39723390, 2024). "Scientific evidence supports the dual functions of miR-205 as a tumor suppressor by affecting ErbB3, VEGFA, and ZEB1/2 in breast, melanoma, and lung cancers, as well as an oncogene by influencing PTEN, TRAF2, and SHIP2 in breast cancer, nasopharyngeal carcinoma, and lung squamous cell carcinoma." (PMID 37692482, 2024). "Recent research shows that the EMT‐TF ZEB1 can facilitate secretory vesicle trafficking via activating exocytotic Rabs to promote the autotaxin‐mediated exhaustion of CD8+ T cells in lung cancer, resulting in immunosuppression in the tumor microenvironment." (PMID 39092293, 2024). "Notably, within the realm of tumor metastasis, treatment with vitamin D has been demonstrated to selectively inhibit the expression of p-STAT3, zinc finger E-box binding homeobox 1 (Zeb1), and Vimentin while enhancing the expression of E-Cadherin." (PMID 38920657, 2024). "Western blot for ZEB1 and SNAIL/SLUG on tumours confirmed these results." (PMID 38515278, 2024). "Herein, we ascertained the levels of some epithelial and mesenchymal markers, particularly transcription factors (ZEB-1, Twist, Snail) and tyms promoter regulator SP1 with TYMS expression in the mesothelioma cancer and non-tumor adjacent tissues by bioinformatics analysis." (PMID 37894370, 2023).